P4HB (prolyl 4-hydroxylase subunit beta)
Description:
This multifunctional protein catalyzes the formation, breakage and rearrangement of disulfide bonds. At the cell surface, seems to act as a reductase that cleaves disulfide bonds of proteins attached to the cell. May therefore cause structural modifications of exofacial proteins. Inside the cell, seems to form/rearrange disulfide bonds of nascent proteins. At high concentrations and following phosphorylation by FAM20C, functions as a chaperone that inhibits aggregation of misfolded proteins. At low concentrations, facilitates aggregation (anti-chaperone activity). May be involved with other chaperones in the structural modification of the TG precursor in hormone biogenesis. Also acts as a structural subunit of various enzymes such as prolyl 4-hydroxylase and microsomal triacylglycerol transfer protein MTTP. Receptor for LGALS9; the interaction retains P4HB at the cell surface of Th2 T helper cells, increasing disulfide reductase activity at the plasma membrane, altering the plasma membrane redox state and enhancing cell migration.
Synonyms: PDI; ERBA2L; PDIA1; PO4DB; PROHB; DSI; GIT; PO4HB; P4Hbeta; CLCRP1; PHDB
Tractability: Small molecule: a drug acting on it is in phase 2 or 3 trials; a structure with a bound ligand is known; a high-quality ligand is known; it has a high-quality binding pocket; it belongs to a druggable protein family. Antibody: UniProt places it where antibodies can reach, with high confidence; UniProt predicts a signal peptide or a membrane-spanning region; its Gene Ontology location is reachable by antibodies, with medium confidence. PROTAC: ubiquitination databases record sites on it; its protein half-life has been measured; a small molecule that binds it is known.
Target class: Isomerase; Enzyme
Chemical probes: ML359
Gene: Protein-coding gene on chromosome 17 (81,843,159 to 81,860,856, reverse strand). Ensembl gene ENSG00000185624.
Subcellular location: Endoplasmic reticulum; Endoplasmic reticulum lumen; Melanosome; Cell membrane
Subcellular location (Human Protein Atlas): Endoplasmic reticulum
Pathways (Reactome):
Metabolism of proteins: Insulin processing; Post-translational protein phosphorylation; Regulation of Insulin-like Growth Factor (IGF) transport and uptake by Insulin-like Growth Factor Binding Proteins (IGFBPs)
Transport of small molecules: Chylomicron assembly; LDL remodeling; VLDL assembly
Immune System: Interleukin-12 signaling; Interleukin-23 signaling
Cellular responses to stimuli: Detoxification of Reactive Oxygen Species
Disease: Maturation of DENV proteins
Extracellular matrix organization: Collagen biosynthesis and modifying enzymes
Signal Transduction: Hedgehog ligand biogenesis
Gene Ontology:
Molecular function: actin binding; integrin binding; procollagen-proline 4-dioxygenase activity; protein binding; protein disulfide isomerase activity; protein heterodimerization activity; protein-disulfide reductase activity; RNA binding; thiol oxidase activity; enzyme binding; protein-containing complex binding
Biological process: cellular response to hypoxia; peptidyl-proline hydroxylation to 4-hydroxy-L-proline; positive regulation of cell adhesion; positive regulation of substrate adhesion-dependent cell spreading; positive regulation of T cell migration; positive regulation of viral entry into host cell; protein folding in endoplasmic reticulum; regulation of oxidative stress-induced intrinsic apoptotic signaling pathway; response to endoplasmic reticulum stress; insulin processing; interleukin-12-mediated signaling pathway; interleukin-23-mediated signaling pathway; protein folding
Cellular component: cytoskeleton; cytosol; endoplasmic reticulum; endoplasmic reticulum lumen; endoplasmic reticulum-Golgi intermediate compartment; external side of plasma membrane; extracellular exosome; focal adhesion; lamellipodium; procollagen-proline 4-dioxygenase complex; protein-containing complex; extracellular region; endoplasmic reticulum chaperone complex; melanosome; plasma membrane
Genetic constraint (gnomAD): Loss-of-function variants: 20 observed, 51.81 expected, observed/expected ratio (o/e) 0.39, 90% interval 0.27 to 0.56. The upper end of that interval is the gene's LOEUF score, 0.56, which puts it in group 2 of 6, group 1 being the genes least tolerant of losing a copy. Missense variants: 597 observed, 664.42 expected, observed/expected ratio (o/e) 0.9, 90% interval 0.84 to 0.96. Synonymous variants: 295 observed, 273.89 expected, observed/expected ratio (o/e) 1.08, 90% interval 0.98 to 1.19.
Homologues: Orthologues: chimpanzee P4HB (99% identical), macaque P4HB (98% identical), mouse P4hb (94% identical), rat P4hb (94% identical), guinea pig P4HB (94% identical), dog P4HB (93% identical), pig P4HB (88% identical), tropical clawed frog p4hb (76% identical), zebrafish p4hb (72% identical), Caenorhabditis elegans pdi-2 (55% identical), Drosophila melanogaster Pdi (53% identical), Caenorhabditis elegans pdi-1 (41% identical), and 5 more. Paralogues in human: PDIA2 (47% identical), PDILT (32% identical), PDIA4 (32% identical), PDIA3 (31% identical), TXNDC5 (22% identical), PDIA6 (22% identical), PDIA5 (21% identical), TMX3 (17% identical), ERP44 (17% identical), TXNDC11 (17% identical), ERP27 (16% identical), TMX4 (12% identical), and 1 more.
Diseases named in the same sentence as P4HB in open-access papers:
P4HB is named in the same sentence as 141 diseases in open-access papers, as found by Europe PMC text mining. Sharing a sentence is not in itself a finding about the gene and the disease. The quoted sentences say what the papers report.
breast carcinoma (20 papers, 2017 to 2025). "COL10A1, which encodes Collagen type X alpha 1, was found to be overexpressed in different types of cancer, such as esophageal cancer and breast cancer, and promoted the malignant progression by upregulating the expression of Prolyl 4-hydroxylase beta polypeptide (P4HB)." (PMID 35910202, 2022). "In addition, it has been mentioned that in breast cancer, COL10A1 promotes cell proliferation, migration, and invasion by targeting prolyl 4-hydroxylase β polypeptide (P4HB)." (PMID 38063927, 2023). "Interestingly, PDIA1 (P4HB) is known to affect the cell surface levels of the non-classical human leukocyte antigen (HLA-G) in breast cancer cell lines (MDA-MB-231 and MCF-7)." (PMID 35159012, 2022).
glioma (17 papers, 2017 to 2023). A benign or malignant brain and spinal cord tumor that arises from glial cells (astrocytes, oligodendrocytes, ependymal cells). "P4HB is also a chaperone protein that has been associated with temozolomide resistance via UPR in gliomas." (PMID 36291587, 2022). "This is the first study that demonstrates the oncogenic roles of P4HB and its underlying mechanism in glioma." (PMID 29069756, 2017). "Having found that P4HB expression was associated with glioma malignant phenotypes, we then performed gain-of-function in vitro assays." (PMID 29069756, 2017). "Mechanistically, the inhibition of P4HB disrupted its protective function and enhanced the sensitivity of glioma cells to TMZ by activating the protein kinase R-like endoplasmic reticulum kinase (PERK) arm of the ER stress response." (PMID 38029391, 2023). "CALR closely interacted with PDIA3 (also known as ERp57) and prolyl 4-hydroxylase β polypeptide (P4HB, also known as PDIA1), which have been reported as prognostic markers in cervical cancer, hepatocellular carcinoma, glioma, and KIRC." (PMID 36338983, 2022). "It has been shown that inhibition of P4HB expression in glioma cells results in suppression of temozolomide resistance by regulating endoplasmic reticulum stress response." (PMID 35436915, 2022). "P4HB promoted proliferation, invasion, migration and angiogenesis in glioma through the mitogen-activated protein kinase (MAPK) signaling pathway." (PMID 35036081, 2022). "As expected, P4HB expression was positively correlated with increasing glioma WHO grade and was significantly up‐regulated in LGG samples with wild‐type IDH compared to LGG samples with mutant‐type IDH." (PMID 32301283, 2020). "High P4HB expression in high grade gliomas was further validated by western blot and end-point PCR analysis at the protein and mRNA levels." (PMID 29069756, 2017). "Future studies will help to delineation the whole picture of P4HB dependent MAPK signaling together with their molecular interactions in glioma malignancy." (PMID 29069756, 2017). "The present study is the first to describe the oncogenic role of P4HB in GBM and the mechanisms underlying its contribution to glioma progression." (PMID 29069756, 2017). "In clinical analysis using human glioma specimens and Gene Expression Omnibus (GEO) profiles, we found that aberrant expression of P4HB was correlated with high-grade malignancy and an angiogenic phenotype in glioma." (PMID 29069756, 2017). "Since tumor invasion and Vascularisation are typical hallmarks in malignant glioma, our findings uncover a promising anti-glioma mechanism through P4HB-mediated retardation of MAPK signal transduction." (PMID 29069756, 2017). "We first assessed cytoplasmic P4HB expression in 64 human glioma specimens based on the staining intensities and percentage of positively stained cells." (PMID 29069756, 2017). "This study is the first to describe the oncogenic effects of P4HB in glioma and the mechanistic linking of P4HB-mediated MAPK activation in glioma progression, invasion and angiogenesis." (PMID 29069756, 2017). "In low-grade glioma with low P4HB expression, microvessels were predominantly pericyte-liked with a capillary phenotype, whereas in high-grade glioma there was hypervascularity with enlarged, branched and disorganized vessel structures." (PMID 29069756, 2017). "Only 12.6% of low-grade glioma cases demonstrated more than 25% of P4HB-stained cells, which was around 30% relative to high-grade glioma (47.9% cases), suggesting that P4HB expression was correlated with glioma malignancy grades." (PMID 29069756, 2017). "Microvessels (arterioles, venules, and capillaries) densities and VEGF staining intensities were significantly stronger in high-grade (high P4HB expression) when compared to the low-grade glioma (low P4HB expression)." (PMID 29069756, 2017).
glioma (continued). "P4HB was found to upregulated in glioma tissues compared to normal tissues." (PMID 38029391, 2023). "Besides, CCK-8 and clonogenic assays indicated that proliferative capacity and clonogenicity of glioma cell lines were attenuated after transfection with PDIA4 or P4HB siRNA." (PMID 34307339, 2021). "Meanwhile, it is also indicated that anti-PDIA4 and/or anti-P4HB therapy may be a novel approach for glioma treatments." (PMID 34307339, 2021). "The prognostic value of P4HB expression in glioma and gastric cancer had been studied, however, its prognostic value in other cancers including kidney cancer is still unknown." (PMID 32003756, 2020). "Recently, we showed that upregulation of P4HB was associated with temozolomide (TMZ) resistance in malignant glioma, and that its inhibition may sensitize chemoresistant glioma to TMZ treatment." (PMID 29069756, 2017). "Notably, P4HB has been proved to be involved in the development of chemoresistance in gliomas." (PMID 38029391, 2023). "The protein disulfide-isomerase P4HB also acts as a chaperone protein involved in protein folding and the ER stress response and is shown to be a prognostic marker of glioma." (PMID 36033825, 2022). "The qRT-PCR and immunohistochemistry confirmed that P4HB, PDIA4 and PDIA5 were overexpressed in gliomas." (PMID 32023222, 2020). "All four genes, P4HB, PDIA4, PDIA5, and TXNDC12, were expressed in glioma cell lines, and these genes were differentially expressed in different cell lines (U251, T98G, A172, U343)." (PMID 32023222, 2020). "The protein expression of P4HB and PDIA4 were higher in glioma tissues compared to normal brain tissues." (PMID 32023222, 2020). "Furthermore, the correlation analysis indicated that the expression of IFI30, an acknowledged biomarker in glioma, was positively correlated with HLA-DMA, P4HB and RCN1." (PMID 35436915, 2022). "We found that knockdown of the P4HB and PDIA4 could significantly reduce the proliferation and migration of glioma cell lines in vitro." (PMID 34307339, 2021). "Besides, the P4HB and PDIA4, which have significant prognostic value in gliomas, were also the important components of the ER stress-related signature." (PMID 34307339, 2021). "Furthermore, the expression levels of several genes (PLOD3, SLC20A1, ADAM9, FBLIM1, SPOCD1, P4HB, PROS1 and SELENON) were positively correlated with glioma grades." (PMID 32091665, 2020). "Serval recent researches has pointed out that P4HB and PDIA4 correlated with the malignant progression of glioma, but these conclusions have not been sufficiently verified by in vitro experiments." (PMID 34307339, 2021).
gastric cancer (16 papers, 2012 to 2025). A primary or metastatic malignant neoplasm involving the stomach. "Emerging evidence suggests an elevated P4HB expression in various cancers and its association with poor prognosis, yet its function in gastric cancer metastasis remains unexplored." (PMID 40534096, 2025). "As a potential therapeutic target, P4HB was found to be a novel diagnostic and prognostic marker for various cancer types, including colon cancer, gastric cancer, and clear cell renal cell carcinoma." (PMID 37845668, 2023). "Upregulation of P4HB has been associated with carcinogenesis and tumor progression in several cancer types, including renal cell carcinoma, gastric cancer, clear cell, and colon cancer." (PMID 36499183, 2022). "Several studies have linked P4HB to various human cancers, including brain, colon, kidney and gastric cancer." (PMID 32903592, 2020). "Our study is the first to identify P4HB as a functional receptor for LGALS9 in gastric cancer, establishing a novel signalling axis in the metastatic microenvironment." (PMID 40534096, 2025). "Functional experiments demonstrated that LGALS9 activation of P4HB promotes gastric cancer cell proliferation, EMT and expression of lipid metabolism genes." (PMID 40534096, 2025). "Pharmacological inhibition of P4HB significantly attenuated these pro‐metastatic effects, suggesting a potential therapeutic strategy for metastatic gastric cancer." (PMID 40534096, 2025). "Our analysis revealed that myeloid cell–derived Galectin‐9 (LGALS9) and its receptor beta‐subunit of prolyl 4‐hydroxylase (P4HB) on epithelial cells constitute a previously uncharacterized ligand–receptor interaction involved in gastric cancer metastasis." (PMID 40534096, 2025). "P4HB expression was significantly expressed in different cancers, such as colon cancer, gastric cancer, bladder cancer, and clear cell renal cell carcinoma." (PMID 39118797, 2024). "In gastric cancer, P4HB was shown to play an important role in regulating invasion and migration in the HIF1α pathway." (PMID 35036081, 2022). "P4HB is overexpressed in different types of tumors, such as hepatocellular carcinoma, non-small-cell lung cancer, and in gastric cancer (GC) for which it has been considered to have a prognostic value." (PMID 32500033, 2020). "Our findings demonstrated that P4HB plays a significant role in the regulatory network of HIF-1α and is closely linked with invasion and metastasis in gastric cancer cells under hypoxic conditions." (PMID 31467922, 2019). "We then observed the effects of inhibition and overexpression of HIF-1α and P4HB on invasion and metastasis in human gastric cancer cell lines." (PMID 31467922, 2019). "Certain types of cancer have been found to exhibit an increase in P4HB, and an excessive expression of P4HB could potentially accelerate the advancement of malignant tumors, such as gastric cancer, clear cell renal cell carcinoma, and colon cancer." (PMID 38305808, 2024). "As reported, P4HB may also serve as a promising chemotherapeutic target for ovarian and gastric cancer cells." (PMID 34620162, 2021). "In gastric cancer (GC), P4HB was found to exhibit a strong correlation with Hypoxia Inducible Factor-1α (HIF1α)." (PMID 38029391, 2023). "Specifically, HIF-1α up-regulates P4HB expression in gastric cancer and together they cooperate to promote GC invasion and metastases." (PMID 32500033, 2020). "Functional experiments confirmed that the activation of P4HB by LGALS9 significantly enhanced proliferation, epithelial‐mesenchymal transition (EMT) and lipid metabolism in gastric cancer cells, while pharmacological inhibition of P4HB reversed these effects." (PMID 40534096, 2025). "To validate the functional relevance of the LGALS9–P4HB interaction, we first examined P4HB expression across normal gastric cell line GES‐1 and various gastric cancer cell lines." (PMID 40534096, 2025).
gastric cancer (continued). "Furthermore, P4HB inhibition downregulated the expression of cholesterol metabolism and PPAR signalling genes in NCI‐N87 cells, supporting the role of P4HB in regulating lipid metabolism in gastric cancer cells." (PMID 40534096, 2025).